RN7SL653P (RNA, 7SL, cytoplasmic 653, pseudogene)
Gene: Miscellaneous RNA gene on chromosome 1 (91,829,774 to 91,830,066, reverse strand). Ensembl gene ENSG00000239794.
Homologues: Orthologues: chimpanzee Metazoa_SRP (98% identical), macaque Metazoa_SRP (96% identical). Paralogues in human: RN7SL1 (77% identical), RN7SL2 (77% identical), RN7SL3 (77% identical), RN7SL444P (75% identical), RN7SL45P (75% identical), RN7SL408P (75% identical), RN7SL448P (75% identical), RN7SL126P (75% identical), RN7SL230P (75% identical), RN7SL493P (75% identical), RN7SL650P (75% identical), RN7SL451P (74% identical), and 703 more.